RRM2 (ribonucleotide reductase regulatory subunit M2)
Diseases named in the same sentence as RRM2 in open-access papers (continued):
Sharing a sentence is not in itself a finding about the gene and the disease.
pancreatic cancer (continued). "Arginine deprivation in pancreatic cancer cells auxotrophic for arginine appears to have multiple effects though we propose the primary mechanism in the chemosensitizing effect in combination with gemcitabine is through E2F-1-mediated regulation of RRM2 following gemcitabine exposure." (PMID 25499121, 2014). "Hence, to study the potential interplay between let-7 and RRM2 and to further explore the opportunity of utilizing let-7 for pancreatic cancer therapeutics, we sought to determine the direct impact of the human let-7 family on RRM2-mediated inherent gemcitabine resistance." (PMID 23335963, 2013). "It has also been shown the anti-pancreatic cancer activity of celastrol by up-regulating DDIT3 and ATF3 and down-regulating RRM2 and MCM4, however, the role of celastrol in anti-pancreatic cancer remains largely elusive." (PMID 38110764, 2023). "In pancreatic cancer, a natural small molecule, astaxanthin, acts via the HIF-1α/STAT3 axis to mediate RRM2, regulating the gemcitabine-induced EMT phenotype." (PMID 36678539, 2022). "For example, in pancreatic cancer cells, Celastrol plays a cytotoxic role by regulating various gene expressions, mainly through ATF3/DDIT3 overexpression and RRM2/MCM4 downregulation." (PMID 36506508, 2022). "It has been reported that RRM2 plays an essential role in cancer cell proliferation and the development of resistance to GEM in pancreatic tumor cells." (PMID 34575569, 2021). "Human pancreatic cancer tissues from 102 patients were subjected to immunohistochemical staining for VASH2 and RRM2." (PMID 28327155, 2017). "We demonstrate that VASH2 is overexpressed in human pancreatic cancer and functions as a gemcitabine-resistance factor by Jun proto-oncogene (JUN) dependent transactivation of ribonucleotide reductase regulatory subunit M2 (RRM2)." (PMID 28327155, 2017). "Treatment of human pancreatic cancer cells with CBL0137 resulted in a dose dependent reduction of protein and mRNA levels of RRM1 and RRM2." (PMID 25402820, 2014). "Recently, it was reported that RRM2, PCNA and MCM2 were downregulated upon treatment with the NSAID NS-398 in pancreatic cancer cells." (PMID 23637916, 2013). "Notably, in PANC-1 pancreatic cancer cells, overexpression of both RRM1 and RRM2 was found to be a necessary requirement for development of resistance to gemcitabine." (PMID 29144412, 2017). "To determine whether the hENT1 × dCK/RRM1 × RRM2 ratio correlated with gemcitabine sensitivity, we examined the relative mRNA expression of hENT1, dCK, RRM1, and RRM2 to GAPDH in eight human pancreatic cancer cell lines." (PMID 17224927, 2007). "Finally, RRM2 may not be a global determinant of drug-resistance in pancreatic cancer cells, in which case the proposed let-7-RRM2-chemoresistance axis may not be as effective as expected in RRM2-dependent resistance." (PMID 23335963, 2013). "Our data demonstrate for the first time that acquired and inherent chemoresistance of pancreatic cancer cells to gemcitabine is determined by the balance of dCK, RRM1, RRM2, and hENT1 gene expression, but not to that of any of the individual genes." (PMID 17224927, 2007).
prostate carcinoma (45 papers, 2009 to 2026). A carcinoma that arises from epithelial cells of the prostate gland. "Targeting RRM2 and the associated signaling pathways holds substantial promise as a therapeutic strategy to enhance the efficacy of docetaxel treatment in prostate cancer." (PMID 37968699, 2023). "We observed a significant association between high RRM2 expression levels and docetaxel resistance in prostate cancer cells." (PMID 37968699, 2023). "RRM2 has been shown to be upregulated in various types of cancer, including prostate cancer, and is associated with poor prognosis and resistance to chemotherapy." (PMID 37968699, 2023). "Our results demonstrated a positive association between RRM2 expression and docetaxel resistance in prostate cancer cell lines and tumor xenograft models." (PMID 37968699, 2023). "We explored the role of Ribonucleotide reductase subunit M2 (RRM2), a gene associated with senescence, in the sensitivity of prostate cancer to docetaxel." (PMID 37968699, 2023). "In prostate cancer, it has been reported that the increased expression of RRM2 was associated with poor prognosis, which was also validated in our study." (PMID 35360870, 2022). "Only 1 of 18 differentially expressed mRNAs (RRM2), which constructed of ceRNA networks, were significantly associated with overall survival in prostate cancer." (PMID 30286759, 2018). "In this study, the higher expression of RRM2 was associated with worse survival outcome in prostate cancer." (PMID 30286759, 2018). "Additionally, HMMR is related to prostate cancer, while RRM2 and CCNB1 shared association with colorectal cancer." (PMID 39118438, 2024). "Finally, high expression of RRM2 was associated with an immunosuppressive tumor-immune microenvironment in both primary prostate cancer and metastatic prostate cancer using CIBERSORT analysis and LM22, a validated leukocyte gene signature matrix." (PMID 32385899, 2020). "RRM2 has been reported to be associated with the occurrence and poor survival of prostate cancer." (PMID 33195193, 2020). "Aberrant overexpression of RRM2 is frequently observed in various aggressive malignancies, including prostate cancer, where it facilitates cellular proliferation, epithelial-mesenchymal transition (EMT), and is associated with poor clinical outcomes." (PMID 41346575, 2025). "We assumed that SNHG4 facilitates prostate cancer cell proliferation, the cell cycle and senescence by regulating RRM2, EZH2, AURKA and TK1." (PMID 37596700, 2023). "Taken together, our findings have substantial implications for personalized treatment approaches in prostate cancer management, potentially leading to more effective therapies and improved patient selection based on RRM2 expression levels." (PMID 37968699, 2023). "This collective evidence underscores the pivotal role of RRM2 as a key regulatory molecule in the onset and progression of prostate cancer (PCA)." (PMID 37968699, 2023). "For example, phosphorylation of RRM1 regulates DNA replication and ATR inhibition vulnerability, while RRM2 drives aggressive prostate cancer and hepatocellular carcinoma, suggesting their importance for targeted therapies 38,39." (PMID 37737478, 2023). "The results provide evidence that RRM2 promotes senescence in prostate cancer cells induced by docetaxel." (PMID 37968699, 2023). "Our study provides novel insights into the key cellular senescence molecule RRM2 and its regulatory role in prostate cancer progression and resistance to docetaxel treatment." (PMID 37968699, 2023). "Our findings align with previous studies demonstrating the involvement of RRM2 in chemoresistance, further emphasizing its importance in prostate cancer progression and treatment response." (PMID 37968699, 2023). "Combination therapies that involve the co-administration of docetaxel with inhibitors targeting RRM2 or the PI3K/AKT pathway present an intriguing avenue to amplify treatment responses in prostate cancer." (PMID 37968699, 2023).
prostate carcinoma (continued). "In our study, we observed a decrease in PI3K/AKT pathway activation following RRM2 knockdown in docetaxel-resistant prostate cancer cells." (PMID 37968699, 2023). "RRM2 has been identified to be overexpressed in prostate cancer and significantly correlated with poor survival of PCa patients." (PMID 37596700, 2023). "Our study provides compelling evidence for the role of RRM2 as a critical regulator of docetaxel sensitivity in prostate cancer." (PMID 37968699, 2023). "Given the prognostic value of RRM2 in prostate cancer, we next examined the expression of RRM2 in our cohort of patients." (PMID 37596700, 2023). "Our findings suggest that RRM2 regulates docetaxel resistance in prostate cancer by stabilizing ANXA1-mediated activation of the PI3K/AKT pathway." (PMID 37968699, 2023). "Knockdown of RRM2 increased the sensitivity of prostate cancer cells to docetaxel, suggesting its role in mediating resistance." (PMID 37968699, 2023). "Our results unequivocally demonstrate that the suppression of RRM2 leads to a substantial reduction in the clonogenic and proliferative capacities of prostate cancer cells." (PMID 37968699, 2023). "Collectively, based on the insights gathered from the preceding discussions, it can be deduced that the ectopic expression of RRM2 plays a pivotal role in contributing to the development of docetaxel resistance in the clinical treatment of prostate cancer." (PMID 37968699, 2023). "The results suggested that high expression of SNHG4 was correlated with RRM2/EZH2/AURKA/TK1 overexpression in prostate cancer tissue specimens." (PMID 37596700, 2023). "Given the clinical significance and biological functions of RRM2 in prostate cancer, we next sought to investigate the lncRNA-mediated regulation of RRM2 in PCa." (PMID 37596700, 2023). "Drug screening experiments on PC3 and DU145 cells revealed that their RRM2 content was significantly higher than other prostate cancer cell lines." (PMID 37968699, 2023). "Clinical Relevance: Our study contributes significantly to our understanding of the clinical relevance of RRM2 expression in prostate cancer." (PMID 37968699, 2023). "An interesting study has demonstrated recently that FOXM1 transcriptionally activates RRM2 in prostate cancer." (PMID 36597126, 2023). "Ribonucleotide reductase small subunit M2 (RRM2), as a master driver of aggressive prostate cancer, showed significant prognostic value of RRM2 in prostate cancer." (PMID 35812443, 2022). "In our study, we develop and validate a prognostic signature (named TILTregSig) composed of five Treg-specific mRNAs (SOCS2, EGR1, RRM2, TPP1, and C11orf54) for prostate cancer, which is associated with RFS in prostate cancer." (PMID 35812443, 2022). "We found that RRM2 was statistically significant to the prognosis of prostate cancer patients (p < 0.05)." (PMID 35360870, 2022). "FOXM1 and E2F1, which have been shown to transcriptionally regulate RRM2 expression in prostate cancer, glioblastomas, and CRC, respectively, were also included." (PMID 34234118, 2021). "For example, in vitro and vivo experiments showed that overexpression of RRM2 promoted epithelial-mesenchymal transition, whereas knockdown of RRM2 inhibited its oncogenic function in prostate cancer." (PMID 33686951, 2021). "CKS2, TK1, MKI67, TOP2A, CCNB1 and RRM2 directly related to the recurrence and prognosis of prostate cancer." (PMID 32266115, 2020). "Increased expression of RRM2 has been demonstrated to be a mechanism driving poor patient outcomes in prostate cancer, in accordance with our findings." (PMID 32180804, 2020). "According to our study, the high expression of PKMYT1 and RRM2 was correlated with prostate cancer oncogenesis and poor prognosis, indicating their potential oncogenic roles in prostate cancer." (PMID 32180804, 2020). "Knockdown of miR‐193b targets FOXM1 and RRM2 in prostate cancer cells phenocopied overexpression of miR‐193b." (PMID 31225930, 2019).
prostate carcinoma (continued). "A number of the top genes identified in this study have previously been implicated in prostate cancer development and progression, Gleason grade, metastases and biochemical recurrence; including CANT1, FBP1, RRM2, POLE2, PDE4D, and ALDH1A3." (PMID 27980733, 2016). "RRM2, up-regulated in four of the seven cancers, has been suggested to be related to esophageal and gastric cancers and prostate cancer, consistent with its critical role in DNA synthesis which must be maintained in rapidly dividing cells." (PMID 21060876, 2010). "Collectively, these findings indicate that TREX1, NOX4, and RRM2 may be significant contributors to the progression of prostate cancer; however, their precise roles and potential therapeutic implications warrant further investigation." (PMID 41346575, 2025). "Targeting RRM2 or ANXA1 may offer a promising therapeutic strategy to overcome docetaxel resistance in prostate cancer." (PMID 37968699, 2023). "Additionally, we conducted preliminary investigations into the role of RRM2 in the process of docetaxel-induced senescence in prostate cancer cells." (PMID 37968699, 2023). "To elucidate the pivotal role of RRM2 in prostate cancer, we meticulously acquired relevant data from comprehensive sources, including the Cancer Genome Atlas (TCGA) database and other pertinent repositories, to investigate the expression levels of RRM2 mRNA across these datasets." (PMID 37968699, 2023). "Loss of RRM2 has been reported to induce cell cycle arrest, cell senescence and SASP phenotypes, and the RRM2 inhibitor COH29 has been proven to exert notable antitumor effects in prostate cancer cells." (PMID 37596700, 2023). "Next, we investigated the biological functions of RRM2 in prostate cancer cell lines." (PMID 37596700, 2023). "The stabilization of ANXA1 by RRM2 may contribute to the development of resistance mechanisms in prostate cancer." (PMID 37968699, 2023). "Similarly, in the clinical samples obtained from our research center, we observed elevated levels of RRM2 in prostate cancer tissue juxtaposed with lower expression levels in adjacent healthy tissue." (PMID 37968699, 2023). "Besides, previous research has demonstrated that several transcription factors, such as FOXM1, MYC, APC/C/CDH1, and E2F, targeted RRM2 in prostate cancer." (PMID 36202136, 2022). "Our previous study elucidated comprehensive molecular mechanisms of RRM2 in prostate cancer (PC)." (PMID 32385899, 2020). "Our real‐time RT‐PCR analyses revealed that CUDC‐907 treatment significantly decreased the transcript levels for CHK1, Wee1, RRM1 and RRM2 in prostate cancer cells, indicating a potential transcriptional mechanism responsible for the down‐regulation of these proteins by the agent." (PMID 32459381, 2020). "Through integrative studies, including CRISPR-Cas9i screening across various prostate cancer cell models, analysis of clinical cancer-specific expression, relevance to patient prognosis, and in vitro loss-of-function validation, we identified three cancer-specific targets: CDC20, RRM2, and DTL." (PMID 41492471, 2026). "Furthermore, a noteworthy observation was made as pretreatment of various prostate cancer cells with docetaxel resulted in increased RRM2 expression.This gene’s potential regulatory influence on drug resistance appears to involve the activation of the AKT signaling pathway." (PMID 37968699, 2023). "Finally, RRM2 has been found to be correlated with the malignant phenotypes of prostate cancer, and bioinformatic analysis suggested that RRM2 may have impacts on tumor microenvironment reconstruction and enzalutamide resistance." (PMID 37596700, 2023). "Thus, we aimed to investigate whether depletion of SNHG4, RRM2, EZH2, AURKA or TK1 can cause prostate cancer cell senescence and affect cell viability." (PMID 37596700, 2023).
prostate carcinoma (continued). "To further confirm the role of CDRs in prostate cancer cell growth, we ablated the endogenous expression of CDC20, RRM2, and DTL with cutting-edge RNA-targeted CRISPR-Cas13." (PMID 41492471, 2026). "Further mechanistic studies revealed that CDC20, DTL, and RRM2 were transcriptionally regulated by the RB1/E2F1 axis, mediating cell cycle progression in prostate cancer." (PMID 41492471, 2026). "While previous studies have highlighted the oncogenic roles of CDC20 and RRM2 in prostate cancer, our work further demonstrates that DTL plays a comparable tumor-driving role in prostate cancer compared with CDC20 and RRM2." (PMID 41492471, 2026). "We retrieved the co-expressed gene list of each of CDC20, RRM2, and DTL across ADPC, CRPC, and NEPC cohorts, which showed 175, 92, and 159 genes significantly co-expressed with CDRs at different prostate cancer stages, respectively." (PMID 41492471, 2026). "Our study uncovered a novel molecular mechanism of lncRNA SNHG4 in driving prostate cancer progression and enzalutamide resistance, revealing the critical roles and therapeutic potential of RREB1, SNHG4, RRM2 and let-7 miRNAs in anticancer therapy." (PMID 37596700, 2023). "In this study,we investigated the roles of RRM2 and the ANXA1 in regulating sensitivity to docetaxel therapy in prostate cancer." (PMID 37968699, 2023). "The expression of RRM2 and NUSAP1 in prostate cancer patients was further verified in PRAD_TCGA datasets." (PMID 37596700, 2023). "Taken together, our results suggested that RRM2 and NUSAP1 were not only correlated with poor prognosis of PCa patients but also very likely to contribute to the progression of prostate cancer." (PMID 37596700, 2023). "Taken together, we demonstrated that RRM2 is overexpressed in PCa tumors and regulates the cell viability, cell cycle and DDR of prostate cancer cells." (PMID 37596700, 2023). "Comprehensive Investigation: Our study comprehensively examined the role of the senescence-related gene RRM2, the ANXA1 protein, and the PI3K/AKT pathway in regulating sensitivity to docetaxel therapy in prostate cancer." (PMID 37968699, 2023). "We evaluated the RRM2 expression, docetaxel resistance, and ANXA1 expression in prostate cancer cell lines and tumour xenografts models." (PMID 37968699, 2023). "First, at the beginning of the study, our analysis revealed RRM2 and NUSAP1 to be strong predictors of prostate cancer, and we believe that NUSAP1 is another interesting gene that is worth investigating." (PMID 37596700, 2023). "Several TFs have been identified for regulating RRM2 transcription in different cancers, such as E2F1 in CRC, BRCA1 and E2F1 in glioblastoma, HPVE7 in cervical cancer, and FOXM1 in prostate cancer, and etc.." (PMID 34234118, 2021). "For instance, BCR-ABL in chronic myelogenous leukemia (CML), TMPRSS2-ETS, SLC45A3-ELK4, and D2HGDH-GAL3ST2 in prostate cancer, LHX6-NDUFA8 and SLC2A11-MIF in cervical cancer, RRM2-C2orf48 in colorectal cancer (CRC), and ASTN2-PAPPAas in esophageal cancer." (PMID 33805149, 2021). "Our mechanistic studies suggest that Bcl‐xL, Bim, CHK1, c‐Myc, Mcl‐1, RRM1, RRM2 and Wee1 play a role in the antitumour activity of CUDC‐907 against prostate cancer." (PMID 32459381, 2020). "To determine our prediction, we found CCNB1, CKS2, MKI67, RRM2, TK1 and TOP2A acted as independent prognostic factors in TCGA prostate cancer." (PMID 32266115, 2020).